PON1 (paraoxonase 1)
Diseases named in the same sentence as PON1 in open-access papers (continued):
Sharing a sentence is not in itself a finding about the gene and the disease.
relapsing-remitting multiple sclerosis (1 paper, 2022). The most common clinical variant of multiple sclerosis, characterized by recurrent acute exacerbations of neurologic dysfunction followed by partial or complete recovery. "PON1 activity has been observed to decrease significantly in the course of relapsing-remitting multiple sclerosis relapses." (PMID 35031011, 2022).
retinal degeneration (1 paper, 2008). Degeneration of the retina. "Since retinal degeneration involves oxidative stress and inhibition of lipid peroxidation protects against light damage Pon1 may have an important role in retinal protection after hypoxic preconditioning." (PMID 18261226, 2008).
sarcoidosis (1 paper, 2026). Sarcoidosis is a multisystemic disorder of unknown cause characterized by the formation of immune granulomas in involved organs. "This study aimed to evaluate the serum PON1 activity in patients with sarcoidosis, its relationship with disease stage, and its association with pulmonary function and routine biochemical parameters." (PMID 41601643, 2026). "Increased oxidative stress in sarcoidosis is known to be associated with clinical outcomes such as alveolar epithelial damage and fibrosis, PON1 deficiency may facilitate the pulmonary effects of sarcoidosis." (PMID 41601643, 2026). "Therefore, while PON1 was associated with sarcoidosis in univariate analysis, its predictive power diminished after accounting for pulmonary function and metabolic factors." (PMID 41601643, 2026). "ROC analysis demonstrated that PON1 provides significant accuracy in distinguishing patients with sarcoidosis from healthy individuals." (PMID 41601643, 2026). "Serum PON1 activity was significantly lower in patients with sarcoidosis than in the healthy controls (p<0.001)." (PMID 41601643, 2026). "This study demonstrated that serum PON1 activity is significantly lower in sarcoidosis patients than in healthy controls." (PMID 41601643, 2026). "Accordingly, the reduction in PON1 observed in our sarcoidosis cohort likely reflects heightened oxidative stress within the granulomatous inflammatory environment but is not unique to sarcoidosis." (PMID 41601643, 2026). "Taken together, these observations demonstrate that PON1 levels decrease with increasing disease severity, highlighting its potential as an activity marker for sarcoidosis." (PMID 41601643, 2026). "Logistic regression analysis revealed that higher BMI and reduced FEV1 were independent predictors of sarcoidosis, whereas PON1 lost significance after adjusting for covariates." (PMID 41601643, 2026). "Serum PON-1 levels in the sarcoidosis patient group were statistically significantly lower than in the healthy control group." (PMID 41601643, 2026). "Previous studies have also reported decreased PON1 activity in patients with active or advanced sarcoidosis." (PMID 41601643, 2026). "In this study, serum PON1 activity was found to be significantly lower in patients with sarcoidosis than in healthy controls." (PMID 41601643, 2026). "Consistent with PLS-DA findings, multivariable logistic regression showed that reduced FEV1 and higher BMI were independently associated with sarcoidosis, whereas PON1 was not significant when these covariates were included." (PMID 41601643, 2026). "ROC curve analysis showed that PON1 could distinguish sarcoidosis patients from controls, with an AUC of 0.838." (PMID 41601643, 2026). "These performance metrics imply that although PON1 alone is not a definitive diagnostic test, it is a promising biomarker for sarcoidosis after further validation." (PMID 41601643, 2026). "Under conditions of heightened oxidative stress, such as chronic granulomatous inflammation in sarcoidosis, reactive oxygen species can directly impair PON1 structure, reduce its catalytic efficiency, or alter HDL composition in a manner that reduces enzyme stability." (PMID 41601643, 2026). "Consequently, systemic oxidative burden may decrease circulating PON1 activity and amplify lipid peroxidation, creating a self-reinforcing cycle that contributes to the pathophysiology of sarcoidosis." (PMID 41601643, 2026). "This broader context supports the interpretation of PON1 as a complementary indicator of oxidative imbalance, rather than a sarcoidosis-specific biomarker." (PMID 41601643, 2026). "While there are some studies on sarcoidosis and its oxidative status, no studies have reported the relationship between PON-1 levels and the stage of this disease." (PMID 41601643, 2026).
secondary hyperparathyroidism (1 paper, 2021). Overproduction of parathyroid hormone in response to influence external to the parathyroid glands. "An impact of secondary hyperparathyroidism on PON1 is also possible." (PMID 33762698, 2021).
septic shock (1 paper, 2019). Shock caused by infection; frequently caused by gram negative bacteria, although some cases have been caused by other bacteria, viruses, fungi, and protozoa; characterized by fever, chills, tachycardia, tachypnea, and hypotension. "Exclusively in septic shock patients, mean PON1 positively correlated with mean temperature (r = 0.53, p = 0.007)." (PMID 30886652, 2019). "Exclusively in septic shock patients, PON1 correlated negatively with LBP (r = −0.42, p = 0.036) and positively with LPS (r = 0.43, p = 0.031) and with patients' temperature, both on the 1st (r = 0.47, p = 0.018) and on the 2nd (r = 0.59, p = 0.002) days." (PMID 30886652, 2019). "In turn, PON1 activities in patients with septic shock or CVI remained stably low." (PMID 30886652, 2019). "Patients with septic shock, CVI, and abdominal MODS had distinctly different dynamics of PON1 during a 5-day follow-up." (PMID 30886652, 2019). "Patients with septic shock, CVI, and abdominal MODS had distinctly different dynamics of PON1 during a follow-up." (PMID 30886652, 2019).
social phobia (1 paper, 2023). An anxiety disorder characterized by an intense, irrational fear of one or more social or performance situations in which the individual believes that he or she will be scrutinized by others. "Our study also revealed an association between PON1 rs705381 and social phobia." (PMID 38275640, 2023). "We also observed statistically significant associations between SOD2 rs4880 and obsessive–compulsive symptoms, PON1 rs705381 and social phobia, IL1B rs1071676 and AUDIT scores, and IL6R rs2228145 and compulsions in alcohol-addicted patients." (PMID 38275640, 2023).
spina bifida (1 paper, 2025). A congenital neural tube defect in which vertebrae are not fully formed. "Overall, the current literature suggests that certain PON1 variants are independently associated with increased spina bifida risk through a mechanism that hinders the ability to detoxify organophosphate pesticides." (PMID 40666233, 2025). "Variations in the PON1 gene can influence an individual’s ability to metabolize these pesticides by altering the catalytic activity of the enzyme, potentially increasing the risk of spina bifida in offspring exposed to these chemicals during pregnancy." (PMID 40666233, 2025). "In addition to PON1/organophosphate pesticide interactions, arsenic, air pollutants, and smoking, other environmental factors such as heavy metals, industrial chemicals, and dietary contaminants have been studied for their interactions with genetic polymorphisms in the context of spina bifida." (PMID 40666233, 2025).
squamous cell carcinoma (1 paper, 2017). A carcinoma arising from squamous epithelial cells. "PON1 expression in LC patient tissues varied between overexpression in squamous cell carcinoma and minimal loss in adenocarcinoma sub-types." (PMID 28467805, 2017).
synovitis (1 paper, 2023). Inflammation of a synovial membrane. "In the current work, measures of HDL function including PON1 activity similarly associated with synovitis by PDUS but did not associate with cytokines or chemokines in the abatacept study." (PMID 36828925, 2023).
thyroid autoimmunity (1 paper, 2025). "From a proteomic perspective, differential expression of proteins such as apolipoprotein D (APOD), paraoxonase 1 (PON1), and heparan sulfate proteoglycans in FF has been shown to predict adverse pregnancy outcomes in subgroups including women with thyroid autoimmunity." (PMID 41226407, 2025).
Tobacco Use Disorder (1 paper, 2022). "Tobacco Use Disorder (TUD) subjects showed lower levels of TRAP than controls, but these effects were no longer significant after considering the interaction between current smoking and PON1 Q192R genotypes." (PMID 35893041, 2022).
toxoplasmosis (1 paper, 2024). A parasitic disease contracted by the ingestion or fetal transmission of toxoplasma gondii. "In this way, it could be understood that theinteraction between the PON1 rs2074351 variant and the low NSEScontext presented a higher risk of toxoplasmosis than their individual effects." (PMID 38285431, 2024). "From the construction of a BN with PTB predictors, an interaction between rs2074351(PON1) and low NSES was identified, which was associated withan increased risk of toxoplasmosis." (PMID 38285431, 2024).
Trypanosoma cruzi infection (1 paper, 2023). "Our findings suggest that paraoxonase-1 levels are reduced in Trypanosoma cruzi-seroreactive dogs without evident clinical signs of Chagas disease, despite their seroreactivity to the other vector-borne diseases studied." (PMID 37368717, 2023).
type 2 diabetic nephropathy (1 paper, 2021). "The TT genotype of PON1 rs705379 independently correlated with type 2 diabetic nephropathy as a cause of end-stage renal disease." (PMID 33762698, 2021).
ulcers (1 paper, 2021). "Treatment with NADA and AM630 protected gastric tissues against ulcers as demonstrated by a decrease in the contents of MDA, TNF-α, MPO, and IL-1β along with an increase in the content of PON-1 activity and GSH in the stomach tissues." (PMID 35083004, 2021).
urothelial carcinoma (1 paper, 2026). A malignant neoplasm derived from the transitional epithelium of the urinary tract (urinary bladder, ureter, urethra, or renal pelvis). "We conducted an exploratory study integrating immunohistochemistry, serum biochemistry, and PON1 genotyping in 39 patients with low-grade (LGUC) or high-grade urothelial carcinoma (HGUC)." (PMID 41750579, 2026).
vector-borne disease (1 paper, 2023). An infectious disease where a pathogen is carried and transmitted by another organism that acts as disease vector. "Results showed a reduction in the serum levels of paraoxonase-1 in Trypanosoma cruzi-seroreactive dogs, either with or without seroreactivity to other vector-borne diseases." (PMID 37368717, 2023).
vitamin D insufficiency (1 paper, 2023). "KOA patients with vitamin D insufficiency had higher levels of MDA, TOS, SOD, OSI, and lower levels of PON-1 and TAC versus KOA patients with sufficient vitamin D status (p < 0.05)." (PMID 36845046, 2023). "The results of the present study indicated that individuals with vitamin D insufficiency had higher levels of MDA, TOS, SOD, and OSI as well as lower levels of PON-1 and TAC." (PMID 36845046, 2023).
cardiovascular disease (160 papers, 2007 to 2025). "The PON1 gene is associated with cardiovascular diseases, oxidative stress in the endothelium, and an increase in free radicals caused by anthracyclines." (PMID 40362292, 2025). "HDL-C is believed to be a stronger risk indicator for CVD than PON1, but another study shows PON1 as a better indicator in men known before with cardiovascular disease." (PMID 38474211, 2024). "To date, polymorphisms in the PON1 gene have been studied in relation to lipid parameters and various cardiovascular diseases." (PMID 39062650, 2024). "In this sense, PON activity is correlated with lung function in cardiovascular diseases and with respiratory problems, especially when PON1 levels are low, and alterations are associated with a decrease in heart rate variability." (PMID 39199265, 2024). "PON1 is a calcium-dependent enzyme associated with high-density lipoprotein (HDL) that protects against cardiovascular disease (CVD) by preventing low-density lipoprotein (LDL) oxidation and detoxifying organophosphates." (PMID 39408985, 2024). "The Q192R PON1 polymorphism and the ε4 allele are both implicated in modifying the risk of cardiovascular disease, secondary to their role in lipid metabolism." (PMID 37415220, 2023). "The importance of the PON1 genotypes was evidenced when some studies reported an association between R and L alleles and a higher risk of cardiovascular disease." (PMID 38136158, 2023). "On the other hand, studies have also found that the presence of the PON-1 R192 allele raises the risk of cardiovascular disease." (PMID 37108044, 2023). "It is also known that low PON-1 activity is a risk factor for the development of cardiovascular disease independently of HDL level." (PMID 36326319, 2022). "Regarding epigenome studies, differentially methylated regions (DMRs) and differentially methylated positions (DMPs) have been associated with the presence of specific genotypes of PON1 and the development of cardiovascular disease." (PMID 35453382, 2022). "Later, another larger meta-analysis consisting of 64 studies including over 19,000 patients and 33,397 healthy individuals has been performed to examine the association between the two PON1 polymorphisms (Q191R and L55M) and cardiovascular disease (CVD)." (PMID 36547064, 2022). "Nowadays, the variation of DNA methylation levels of PON1 has been linked to the development of diseases, such as vascular dementia and cardiovascular diseases, among others." (PMID 35453382, 2022). "In the current study, we sought to examine if PON-1 plays a mechanistic role in the pathophysiology of cardiovascular disease associated with CKD." (PMID 36140402, 2022). "An allele of the PON1 (Paraoxonase 1) gene has been linked to a higher risk of cardiovascular diseases and also underrepresented in centenarians." (PMID 35754110, 2022). "PON1 is an HDL-associated enzyme considered as a potential therapeutic for cardiovascular disease, but the precise mechanisms by which PON1 exerts its systemic anti-inflammatory and antioxidant effects are not well understood or defined." (PMID 35326206, 2022). "Epidemiological evidence shows that low hydrolytic activity of PON1 is associated with an increased risk of cardiovascular disease." (PMID 35327606, 2022). "Association of myeloperoxidase (MPO) with HDL has been implicated in the loss of PON1 activity in cardiovascular diseases." (PMID 34331945, 2021). "Two key polymorphisms in the PON1 gene (L55M and Q192R polymorphisms) alter its expression and activity and have been associated, albeit inconsistently, with risk for cardiovascular diseases." (PMID 34331945, 2021). "This proposition is further supported by the observation that a decreased PON-1 enzyme activity has been linked to an increased risk of cardiovascular disease." (PMID 32854225, 2020).
cardiovascular disease (continued). "IPA identified two top-scoring biological networks associated with human PON1-Q192R polymorphism: “Lipid Metabolism, Molecular Transport, Small Molecule Biochemistry” and “Cardiovascular Disease, Neurological Disease, Organismal Injury and Abnormalities”." (PMID 33260536, 2020). "Generally, PON1 rs662 was associated with slightly increased cardiovascular disease risk, especially in the recessive genetic model, while PON1 rs854560 was associated with somewhat decreased risk in meta-analyses, consistent with our results." (PMID 33425072, 2020). "Further, the PON1 c.575G allele was referred to as a risk allele in some clinical studies concerning cardiovascular diseases." (PMID 32961879, 2020). "The “cardiovascular disease, neurological disease, organismal injury and abnormalities” network, identified from analysis PON1-192QQ vs. RR, was associated with PON1-192RR polymorphism." (PMID 33260536, 2020). "A lot of studies also investigated the influence of PON1 polymorphisms on the risk of developing different cardiovascular diseases." (PMID 33425072, 2020). "The putative anti-atherogenic properties of PON1 stem from meta-analyses of human population studies that consistently show decreased PON1 activity to be associated with cardiovascular disease (CVD) risk." (PMID 31480611, 2019). "Descriptions relating paraoxonases to cardiovascular diseases began around 30 years ago with the association of decreased PON-1 activity with the development of atherosclerotic plaque." (PMID 31052559, 2019). "High risk of cardiovascular disease would not only derive from altered PON1 activitybut also from the presence of a more atherogenic lipoprotein profile in SACchildren." (PMID 28853330, 2018). "Epidemiological evidence demonstrates that low PON1 activity is associated with increased risk of cardiovascular events and cardiovascular disease." (PMID 30151068, 2018). "Different PON1 genotypes have been investigated as markers of susceptibility to cardiovascular disease." (PMID 27812605, 2016). "Paraoxonase 1 (PON1) polymorphisms are associated with an increased susceptibility to cardiovascular disease." (PMID 27812605, 2016). "An atherogenic lipid profile and increased incidence of cardiovascular disease have been described in individuals homozygous to the PON1*192R allele." (PMID 27812605, 2016). "Paraoxonase-1, a high-density lipoprotein linked enzyme complex, was shown to be decreased in several cardiovascular diseases." (PMID 25929926, 2015). "We evaluated the association of indices of paraoxonase (PON1) and oxidative status with subclinical cardiovascular disease (CVD) in mixed-ancestry South Africans." (PMID 24799979, 2014). "Paraoxonase-1 (PON1) is a serum protein, the activity of which is related to susceptibility to cardiovascular disease and intoxication by organophosphorus (OP) compounds." (PMID 22720164, 2012). "PON1 192 and 55 polymorphisms have been widely investigated especially for their possible involvement in the onset or severity of cardiovascular disease (CVD)." (PMID 22536511, 2012). "PON1 55 polymorphism is currently investigated for its possible involvement in cardiovascular diseases." (PMID 22536511, 2012). "Epidemiological evidence demonstrates that low PON1 activity is associated with increased risk of cardiovascular events and is an independent risk factor for cardiovascular disease." (PMID 22548179, 2012). "Research into PON1 has increased exponentially over the past few years because many studies associate this enzyme with inflammation and cardiovascular disease." (PMID 20334696, 2010). "Furthermore, human studies have shown that PON1 gene expression and serum activity inversely correlate with cardiovascular disease risk." (PMID 41181110, 2025).